INS (insulin)
Diseases named in the same sentence as INS in open-access papers (continued):
Sharing a sentence is not in itself a finding about the gene and the disease.
type 2 diabetes (continued). "The worldwide prevalence of type 2 diabetes mellitus (T2DM) and its associated complications resulting from insufficiency of insulin secretion and resistance have increased noticeably and tremendously contribute to the global burden of disability and mortality." (PMID 35097119, 2022). "Hence, vitamin D deficiency is associated with a decreased insulin release, inducing insulin resistance which leads to type 2 diabetes mellitus (T2DM)." (PMID 35804367, 2022). "At END, males showed impaired glucose tolerance and insulin sensitivity compared to females, together with increased type II diabetes pathway activity and higher circulating level of PAI-1." (PMID 36195702, 2022). "Serpentine effectively enhanced the regulation of blood glucose by insulin in our HFD/STZ-induced type 2 diabetes mouse model." (PMID 36678512, 2022). "We used blinded continuous glucose monitoring (CGM) and self-report to compare hypoglycemia rates and duration in 179 type 2 diabetes patients treated with sulphonylureas (n=100) and insulin (n=51) in comparison with those treated with metformin only (n=28)." (PMID 35450869, 2022). "Patients with type 2 diabetes regularly using the tool had improved metabolic control over two years, with a pronounced response in a pathophysiological subgroup of obese insulin-resistant individuals." (PMID 35545657, 2022). "Aerobic and strength-resistance home-based programs had beneficial effects on insulin sensitivity and glycemic control in type 2 diabetes." (PMID 35410000, 2022). "The pooled prevalence was 27% (95% CI: 17%–37%) in type 2 diabetes with higher insulin requirement (1 group) and 15% (95% CI: 1%–40%) in patients with lower insulin requirement (2 group)." (PMID 36213198, 2022). "Recent studies have compared the effect of HIIT with endurance training on insulin sensitivity in patients with type 2 diabetes using surrogate markers of insulin sensitivity such as HOMA-IR." (PMID 36387850, 2022). "Prolonged exposure of cells to insulin induces insulin receptors (INR) down-regulation via internalization and enhanced protein degradation, which causes an imbalance and can lead to type 2 diabetes in humans and other associated diseases." (PMID 36009412, 2022). "For patients with asthma and type 2 diabetes, the effect of insulin on asthma control should be carefully considered while controlling blood glucose." (PMID 36107629, 2022). "The aim of the present study was to evaluate the effect of 18‐week monotherapy with imeglimin on glucose tolerance and on insulin secretion/sensitivity in type 2 diabetic (T2D) patients." (PMID 36239048, 2022). "Pioglitazone is a peroxisome proliferators-activated receptor gamma (PPAR) agonist and putative insulin sensitizer approved for the treatment of type 2 diabetes due to its efficacy on reducing plasma glucose." (PMID 35928268, 2022). "Second, findings of the FIadjBMI–PCOS and type 2 diabetes–PCOS (univariable MR and multivariable MR) causal associations suggest the importance of controlling fasting insulin levels to mitigate the risk of developing PCOS, irrespective of BMI." (PMID 35771237, 2022). "V-Go is an insulin delivery system available only through prescription for patients with type II diabetes who need to take insulin to maintain their blood glucose levels." (PMID 36381916, 2022). "A reduced expression pattern of membrane fusion proteins was found in type II diabetes patients' islets, indicating that the fusion defect is closely related to insulin‐based metabolic diseases." (PMID 36111501, 2022). "Patients with PDX1–MODY with type 2 diabetes have been shown to be effectively treated with metformin, dipeptidyl peptidase–4 inhibitors, and insulin, which are all options for treating individuals with MODY 4 in case reports." (PMID 36573710, 2022). "Renet al., on the other hand, discovered that in type 2 diabetes patients with the AA genotype, plasma levels of leptin and insulin were much lower than those with the GA or GG genotypes." (PMID 36128550, 2022).
type 2 diabetes (continued). "A sub-analysis of the trial evaluated the potential benefit of CGM in older adults (those aged >60 years) living with either type 1 or type 2 diabetes, with an HbA1C of 7.5–10% and on multiple daily doses of insulin." (PMID 36694891, 2022). "Our findings implicate additive effects across pathophysiological pathways involved in type 2 diabetes, including glycolysis, gluconeogenesis, and insulin secretion." (PMID 35657990, 2022). "Due to the early age of onset and insufficient insulin secretion, these patients are easily misdiagnosed as type 1 diabetes or type 2 diabetes." (PMID 36181023, 2022). "On the other hand, the removal of the p16Ink4a-expressing senescent cells either genetically (using the INK-ATTAC model) or pharmacologically (ABT-263, a Bcl-2 inhibitor) restored glucose tolerance and insulin sensitivity in the type 2 diabetes model." (PMID 35563231, 2022). "The works discussed in this section refer to the use of silica nanoparticles as nanocarriers for antidiabetic drugs other than insulin for type 2 diabetes treatment." (PMID 36671612, 2022). "Type 2 diabetes (T2D) is the result of insufficient production of the glucose-lowering hormone insulin, triggered by multiple factors." (PMID 34890851, 2022). "Other studies have found that stevia glycoside can improve glucose and insulin tolerance in type 2 diabetic rats and restore their elevated fasting glucose, serum insulin, and lipid levels to normal." (PMID 36034890, 2022). "The insulin-sensitizing effect of tirzepatide appears to be relatively more potent in mice with diet-induced obesity than in human subjects with type 2 diabetes." (PMID 36050763, 2022). "Type 2 diabetes (T2D) is a steadily growing metabolic disease worldwide, characterized by a decline in insulin secretion from pancreatic β-cells and impaired insulin function in insulin-target tissues, such as skeletal muscle." (PMID 35270128, 2022). "In type 2 diabetes, improvements in skeletal muscle size and quality have been accompanied by reductions in visceral fat and improvements in insulin sensitivity and glucoregulation as a result of progressive resistance training (PRT)." (PMID 35547420, 2022). "Alternatively, Gerald Reaven confirmed the work of Himsworth, demonstrating relative insulin resistance in type 2 diabetes." (PMID 35163746, 2022). "Many studies have shown positive effects of training on insulin-mediated glucose uptake in skeletal muscle in patients with type 2 diabetes, and with the present protocol we aimed to mimic the oscillations in energy stores seen with frequent exercise training." (PMID 36531168, 2022). "Adiponectin, which exerts beneficial effects on insulin sensitivity and anti-inflammatory activity, is downregulated in settings of type 2 diabetes and obesity." (PMID 35928844, 2022). "IGFBP-1 is higher in individuals with type 1 diabetes (hypoinsulinemic), decreased in those with type 2 diabetes (hyperinsulinemic), and significantly diminished by insulin administration." (PMID 35586622, 2022). "In the treatment of type 2 diabetes, insulin is recommended only in later stages and remains covered by the National Health Insurance at a rate of 100%." (PMID 36033350, 2022). "In turn, the impaired ability of insulin to inhibit glucose production in MS patients leads to the occurrence of hyperglycemia and increased insulin secretion, which may lead to the development of type II diabetes, which may predispose to the progression of NAFLD." (PMID 35600209, 2022). "There are two types of hyperglycemia; Type-1 and type-2 diabetes, triggered by a decreased level of insulin and inefficient utilization of insulin, respectively." (PMID 36293291, 2022). "In our study, the treatment of male patients with type 2 diabetes with 10 mg of melatonin for 3 months before bedtime reduces insulin sensitivity." (PMID 35619221, 2022).
type 2 diabetes (continued). "Glucagon-like peptide-1 (GLP-1) is an effective potential target for treating type 2 diabetes, stimulating insulin secretion, and regulating blood sugar levels." (PMID 36479195, 2022). "GLP-1RA is widely used to treat type 2 diabetes by enhancing insulin production, and they also have the added benefit of suppressing appetite and losing weight." (PMID 36569936, 2022). "Although CGM was previously reported to be cost‐effective compared to SMBG in patients with type 1 or type 2 diabetes on insulin therapy, these studies were mostly conducted in developed countries, and relevant data in China is scarce." (PMID 36251516, 2022). "Co-payments are unlikely to be the most influential factor behind persisting inequalities in insulin initiation among individuals with type 2 diabetes in Finland." (PMID 36033350, 2022). "The insulinotropic effect of GIP is diminished in patients with type-2 diabetes but is restored upon near normalization of glycemia upon 4-week administration of insulin." (PMID 35299971, 2022). "Insulin therapy continued during the post-operative period in 7 patients with type 1 diabetes and two patients with type 2 diabetes." (PMID 36402951, 2022). "The human insulin gene is hypermethylated at the TSS + 63 position, corresponding to the rat INS2 2-UP2 region, in type 2 diabetic patients, and this hypermethylation is correlated with decreased INS mRNA40." (PMID 35562179, 2022). "The current study investigated the effects of C. lacerata on fasting glucose, Hba1c, insulin resistance indices, and lipid profile on patients with type 2 diabetes." (PMID 35242882, 2022). "Type II diabetes mellitus results from resistance to insulin and the inability of the body to secrete enough insulin as compensation." (PMID 35530852, 2022). "As patients with type II diabetes show significant insulin resistance to exogenous GIP, these pigs are good models to study the role of GIP in glucose homeostasis and pancreatic development." (PMID 35343091, 2022). "If our results are replicated, we recommend that patients with type 2 diabetes limit their use of melatonin in high doses, as reduced insulin sensitivity is central to the pathophysiology of type 2 diabetes." (PMID 35619221, 2022). "SPARC is required to maintain glucose homeostasis and insulin secretion in mice with metabolic diseases such as obesity and type 2 diabetes." (PMID 35721704, 2022). "Insulin degrading enzymes are lower in carriers of ApoE ε 4, which alter insulin signaling and clearance of Aβ in Type 2 Diabetes and AD." (PMID 35336756, 2022). "Type-2 diabetics have insulin resistance in their bodies, which prevents their cells from taking glucose from the blood, resulting in hyperglycaemia or high blood glucose levels." (PMID 35269321, 2022). "Correlation between plasma insulin and bladder and bladder/body weight across animal models of type 2 diabetes." (PMID 36003651, 2022). "Unfortunately, hyperinsulinemia is almost inevitable for better glucose control because more than 80% of type 2 diabetes patients are resistant to insulin." (PMID 35090539, 2022). "Humans with type 2 diabetes manifest defective insulin secretion and action and are often overweight or obese." (PMID 36014488, 2022). "On the other hand, when the production of insulin is insufficient, there is an increase in hyperglycemia and the development of type 2 diabetes, a disease leading to multi-organ damage." (PMID 36012251, 2022). "This has endeavored through the development and testing of a telemedicine solution for patients with type 2 diabetes who are on insulin therapy." (PMID 36476605, 2022). "Type 2 diabetes develops when the body becomes resistant to the effect of insulin or the body’s ability to produce insulin gradually decreases over time; it usually develops in middle age and older people." (PMID 36483768, 2022).
type 2 diabetes (continued). "This is probably explained by the higher fasting basal glucose levels of 9.1 mMol/L in their more heterogenic type 2 diabetes group on glicazide and insulin medication." (PMID 36225127, 2022). "The results demonstrated that vitamin D decreased blood glucose levels and enhanced insulin sensitivity in type 2 diabetics." (PMID 35844355, 2022). "Further, the study also showed that oral anti-diabetic drugs were used more frequently than injectable insulin because many patients were diagnosed as type II diabetes mellitus." (PMID 36705114, 2022). "Insulin is one of the key players of a vicious circle perpetuating type 2 diabetes and Alzheimer’s disease." (PMID 36819480, 2022). "In patients with type 2 diabetes and obesity, a phase 2 study has shown that bimagrumab increased the lean mass and enhanced insulin sensitivity." (PMID 35964012, 2022). "Taking together, our results reveal that miR-21 in islet β cell promotes insulin secretion and support a role for miR-21 in the regulation of pancreatic β cell function in type 2 diabetes." (PMID 35729232, 2022). "Patients with type 2 diabetes are insulin resistant, and so there is still a need to find drugs that can help to increase insulin sensitivity." (PMID 35566124, 2022). "Diverse PTPs, such as PTPN1, PTPN2, PTPN9, PTPN11, PTPRS, and DUSP9, have been reported to attenuate insulin signaling and trigger type 2 diabetes, indicating that PTPs are promising drug targets for the treatment or prevention of type 2 diabetes." (PMID 35204821, 2022). "Pancreatic β-cells are crucial for controlling glucose homeostasis by properly producing and secreting the glucose-lowering hormone insulin, and the dysfunction of β-cells determines the outcomes for both type 1 and type 2 diabetes." (PMID 35563231, 2022). "Here, we show that TGS1 is upregulated by insulin and upregulated in islets of Langerhans from mice exposed to a high-fat diet and in human β-cells from type 2 diabetes donors." (PMID 35041827, 2022). "Insulin signaling in the liver and β-cell has emerged as the major determinant in preventing type 2 diabetes through the integrative role of molecules like IRS2 and FOXO, thus preventing β-cell dedifferentiation." (PMID 36361703, 2022). "For example, the PI3K/Akt pathway damaged in various body tissues leads to obesity and type 2 diabetes as the result of insulin resistance; in turn, insulin resistance exacerbates the PI3K/Akt pathway, forming a vicious circle." (PMID 36330088, 2022). "Accordingly, treatment with AMPK activator metformin, compared to insulin/sulphonylurea therapy, was associated with milder GBS symptoms in patients with type 2 diabetes mellitus." (PMID 36139470, 2022). "Electron microscopic analysis showed the abnormal accumulation of autophagosomes in MIN6 cells, a mouse insulin-secreting cell line, loaded with high free fatty acids or high glucose and in human islets from type 2 diabetic patients." (PMID 35625542, 2022). "Exogenous insulin was recommenced on day 660 due to the development of type 2 diabetes-like changes, possibly related to weight gain over the course of the experiment (from 10.7 kg to 18.1 kg)." (PMID 35784286, 2022). "Even people who are just close relatives of people with type 2 diabetes often have impaired insulin oscillatory patterns." (PMID 35163806, 2022). "Metformin, glycosidase inhibitors, and basal insulin were the most used among type 2 diabetes inpatients." (PMID 35707460, 2022). "In particular, the potential effects of an increase in insulin blood concentrations are relevant because saxagliptin is prescribed for its glucoincretin effect in patients with type 2 diabetes." (PMID 36461653, 2022). "The aim of this population-based study was to assess the impact of insulin treatment on cancer incidence in subjects with type 1 or type 2 diabetes in Italy." (PMID 35681699, 2022).
type 2 diabetes (continued). "By 2010 the number of insulin users had increased to 6.7/1000, and 4.3/1000 of them were deemed to have type 2 diabetes; a sixfold increase." (PMID 35275238, 2022). "The largest genome-wide association study (GWAS) for LADA found that most loci were associated with type 1 diabetes (e.g. HLA, INS, PTPN22), although some genes such as TCF7L2 were shared by LADA and type 2 diabetes." (PMID 35953726, 2022). "As formerly mentioned, insulin resistant subjects with type 2 diabetes are reported to have low bone turnover." (PMID 35422766, 2022). "In conclusion, glimepiride combined with recombinant human insulin injection has a higher application value in the treatment of patients with type 2 diabetes." (PMID 35571731, 2022). "Primary BAs have been shown to delay disease progression in type 2 diabetic mice by regulating glucose and lipid metabolism and improving insulin sensitivity." (PMID 36186976, 2022). "Here, we extensively investigated the effects of TRE on hepatic glycogen levels and insulin sensitivity in individuals with type 2 diabetes." (PMID 35871650, 2022). "Specific therapies aiming at reversing the β-cell dysfunction and improving insulin sensitivity in patients with type 2 diabetes are needed." (PMID 36531168, 2022). "On the other hand, type 2 diabetes is a metabolic disorder in which pancreatic beta-cell failure is accompanied by insulin resistance, resulting in an organism that is resistant to the insulin it produces." (PMID 35682790, 2022). "Skeletal muscle insulin resistance is considered the primary defect leading to the development of type 2 diabetes making skeletal muscle the ideal tissue to identify metabolic defects contributing to insulin resistance." (PMID 36111162, 2022). "This study investigated the barriers and facilitators to insulin treatment from the perspectives of patients with type 2 diabetes following treatment at Dessie Comprehensive Specialized Hospital, North-East Ethiopia." (PMID 35854336, 2022). "Aerobic exercise interventions are uniquely efficacious as they promote glucose uptake through a non-insulin-dependent mechanism that is intact in people with type 2 diabetes." (PMID 35930075, 2022). "The present study suggests that the glucagon test is more useful than other tests for assessing endogenous insulin secretory capacity in type 2 diabetic patients requiring hospitalization." (PMID 35574023, 2022). "Insensitivity to insulin is a characteristic of type II diabetes, which accounts for 85-90 percent of all diabetic patients." (PMID 36589630, 2022). "Type II diabetes mellitus is distinguished by showing resistance to insulin and the abnormalities present in the β cells, presenting a decrease in the production and secretion of insulin." (PMID 36014575, 2022). "Some studies showed that type 2 diabetes also occurs due to the body's inability to use insulin, and most of the time as a result of being overweight and physical inactivity, with symptoms similar to those of type 1." (PMID 36188660, 2022). "Type 2 diabetes mellitus (T2DM) is characterized by insufficient insulin production or the inability to absorb it for glycemic regulation in the human body." (PMID 36407540, 2022). "In type 2 diabetes, initiation of newer antidiabetics is, in most cases, recommended before insulin." (PMID 36033350, 2022). "In another study, the 25% of the subjects with the highest insulin response to a glucose challenge at baseline had after 15 years follow-up an increased incidence of impaired glucose tolerance and type 2 diabetes." (PMID 34360563, 2021). "Most participants (72%) reported having type 2 diabetes, and more than half of participants (57%) received antidiabetic treatment including insulin or another injectable." (PMID 33691691, 2021). "The LCCP family portal is effective for glycemic control and self-management behavior improvement in patients with type 2 diabetes receiving insulin therapy." (PMID 33544081, 2021).